EZH2 (enhancer of zeste 2 polycomb repressive complex 2 subunit)
Diseases named in the same sentence as EZH2 in open-access papers (continued):
Sharing a sentence is not in itself a finding about the gene and the disease.
glioblastoma (continued). "Ultimately, EZH2 directly regulates STAT3, and its inhibition may impair key signaling pathways that promote tumor growth and maintain a stem-like tumor cell population in glioblastoma." (PMID 38183103, 2024). "Therefore, to explore whether PRMT6 has a regulatory effect on EZH2 in glioblastoma cells, we examined the influence of PRMT6 silencing or overexpression on EZH2 expression." (PMID 39043634, 2024). "Integrated analyses demonstrated that mTORC1 increased the protein expression of EZH2, while mTORC2 controlled the production of SAM in human glioblastoma (GBM)." (PMID 38727317, 2024). "However, our co-IP assays did not detect the interaction between EZH2 and p65 in glioblastoma cells." (PMID 36263173, 2022). "Our study demonstrated that combined targeting of NF-κB and EZH2 with CAPE and EPZ-6438 respectively have synergistic suppression of cancer in vitro and in vivo and therefore provides information for devising strategies of Synergistic effect for the treatment of glioblastoma." (PMID 36263173, 2022). "EZH2 inhibition in glioblastoma induced an increase in M1 markers (iNOS and TNF-α) and reduction in M2 markers (tumor growth factor-β1, -β2, and stabilin-1) in both murine microglia and human peripheral blood mononuclear cell-derived macrophages, which is indicative of the pro-M2 function of EZH2." (PMID 34737746, 2021). "The analyses revealed that SATB2, EZH2, SUZ12, and PCL3 are enriched in older patients with glioblastoma (GBM) with worse performance status." (PMID 33124191, 2020). "Through suppression of several oncogenes including p-AKT, EZH2, XIAP, CDK6, cyclin-D1 and cyclin-D2, overexpression of miR-340 inhibits cancer cell proliferation, migration and invasion, induces apoptosis and autophagy in glioblastoma and miR-340 is a marker for glioblastoma diagnosis and prognosis." (PMID 27036021, 2016). "Here we report that EZH2 is up-regulated in angiogenic endothelial cells and that miR-101 is down-regulated in primary endothelial cells exposed to VEGF or glioblastoma cells, as well as in blood vessel endothelial cells that were isolated from vascularized glioblastomas from patient samples." (PMID 21297974, 2011). "Upon examination of the EZH2 immunohistochemistry of vascularized glioblastoma and non-neoplastic brain tissue slices, we noticed positive nuclear staining for EZH2 in the endothelial cells of newly formed blood vessels in the glioblastoma samples, but not in the non-neoplastic brain tissues." (PMID 21297974, 2011). "In addition, glioblastoma cells were treated with a PRMT6 inhibitor (EPZ020411) for 48 h, and it was found that EZH2 protein expression in glioblastoma cells was significantly inhibited, suggesting that PRMT6 may regulate the expression level of EZH2 through post-translational modification." (PMID 39043634, 2024). "Xenograft tumor assay and HE staining results showed that the expression of PRMT6 could promote the invasion of glioblastoma cells in vivo, the immunohistochemical staining results of mouse brain tissue tumor sections also confirmed the regulatory relationship between PRMT6, TRAF6, and EZH2." (PMID 39043634, 2024). "However, it has been reported that lncRNA NEAT1 can affect glioblastoma cell growth and invasion by inducing trimethylation of H3K27 in the promoter regions of Axis inhibition protein 2, inhibitor of β-catenin and T cell factor, and glycogen synthase kinase 3B or by regulating EZH2 levels." (PMID 32157157, 2020). "Gene expression analysis of glioblastoma (GBM) cells lacking EZH2 showed that PRC2 regulates hundreds of interferon-stimulated genes (ISGs)." (PMID 31513636, 2019).
glioblastoma (continued). "In glioblastoma multiforme (GBM), inhibition of EZH2 by S-adenosylhomocysteine hydrolase (SAH) inhibitor 3-deazaneplanocin A (DZNep) was able to reduce self-renewal and tumor-initiating capabilities of GBM CSCs in vivo via affecting transcriptional regulation of oncogene MYC." (PMID 28148257, 2017). "Importantly, H3-WT glioblastoma (GBM) lines, or those with G34R mutations, were not affected by EZH2 inhibitors, demonstrating the specific H3K27M context required for EZH2 inhibitor efficacy." (PMID 34944870, 2021). "It has been reported that the histone methyltransferases EZH2, which methylates H3K27, modifies the nonhistone protein by directly binding to STAT3 in glioblastoma." (PMID 31636512, 2019). "EZH2 has also been shown to methylate non-histone substrates; EZH2-mediated methylation of STAT3 leads to STAT3 activation and increased glioblastoma tumorigenicity." (PMID 30022044, 2018). "The phosphorylated-EZH2 complex targets crucial nonhistone substrates, for example, S21 phosphorylation of EZH2 enhances EZH2-mediated STAT3 methylation due to a stronger interaction with STAT3 in glioblastoma multiforme (GBM) stem-like cells." (PMID 39769907, 2024). "Interestingly, although nuclear p-STAT3 was involved in EZH2 transactivating action, p-STAT3 as well as STAT3 were not methylated in PDAC, which is different from other cancer cell types that methylated STAT3 by EZH2 is involved in tumorigenesis of glioblastoma stem-like cells." (PMID 34771469, 2021).
colorectal cancer (184 papers, 2006 to 2026). A primary or metastatic malignant neoplasm that affects the colon or rectum. "For example, the aberrant expression of histone methyltransferases, such as enhancer of zeste 2 polycomb repressive complex 2 subunit (EZH2), has been implicated in the progression of breast and colorectal cancers." (PMID 40579593, 2025). "Epigenetic modulation by EZH2 of immune-related genes is implicated in the carcinogenesis of different cancer types, including colorectal cancer." (PMID 39946195, 2025). "Elevated enhancer of zeste homolog 2 (EZH2) expression in colorectal cancer (CRC is associated with chemoresistance)." (PMID 40314246, 2025). "Silencing of ST6GalNAc6 is induced by the NF-κB-mediated YY1/PRC2/EZH2 axis, which binds to its promoter and represses activity, leading to loss of immunosuppression and promotion of colorectal cancer progression." (PMID 33406733, 2021). "Take for instance, targeting histone methyltransferase EZH2 (zeste homolog 2) significantly alleviates intestinal inflammation, EZH2 is correlated with colorectal cancer stage and prognosis, linked to CRC tumorigenesis." (PMID 33469000, 2021). "EZH2 overexpression has been associated with poor survival in breast, prostate, and colorectal cancers, and studies for EOC have yielded similar results." (PMID 34140011, 2021). "GSK126 increases the number of myeloid-derived suppressor cells (MDSCs) and decreases CD4+ and IFNΥ CD8+ T-cells, which is associated with antitumor immunity in colorectal cancer, via EZH2-mediated H3k27me3 levels." (PMID 34901003, 2021). "Inversely, LINC00628 is downregulated in colorectal cancer, which is associated with poor prognosis, and its interaction with EZH2 leads to p57 upregulation." (PMID 33117811, 2020). "As an epigenetic regulator, EZH2 is highly expressed in a variety of malignant tumors and associated with poor prognosis of tumors including colorectal cancer,bladder cancer, non-small cell lung cancer 27-29." (PMID 32047553, 2020). "In a series of 119 colorectal cancer tissues and their adjacent normal counterparts, immunohistochemical analysis of EZH2 showed that 69.7% of cases overexpressed EZH2, and overexpression was associated with advanced TNM stage and increased depth of invasion." (PMID 33050946, 2020). "Some studies reported that MALAT1 inhibited E-cadherin expression by binding to highly expressed EZH2 at its 3′ end in colorectal cancer, thereby caused tumor cell epithelial-mesenchymal transition (EMT) and oxaliplatin resistance." (PMID 31391118, 2019). "Polymorphisms in EZH2 have been identified to be associated with multiple cancers, such as bladder cancer, Oral squamous cell carcinoma and colorectal cancer." (PMID 29212262, 2017). "This is the first study of genetic polymorphism in exon region of EZH2 and risk of colorectal cancer." (PMID 29212262, 2017). "In the current study on patients with colorectal cancer who underwent surgical treatment, we elucidated the association of EZH2 expression, gene mutations, or miR-31 expression in the pathway downstream of EGFR with the efficacy of anti-EGFR therapy." (PMID 28147317, 2017). "Here we report a case control study for a missense variant in EZH2 and colorectal cancer susceptibility." (PMID 29212262, 2017). "In conclusion, EZH2 expression was associated with survival in patients with colorectal cancer who were treated with anti-EGFR therapeutics." (PMID 28147317, 2017). "Polymorphisms in EZH2 has also been reported to be associated with multiple cancer, including colorectal cancer." (PMID 29212262, 2017). "With regard to the association between EZH2 expression and outcomes in patients with colorectal cancer, previous studies have reported that EZH2 overexpression was associated with a favorable prognosis." (PMID 26871294, 2016). "In contrast, previous studies on colorectal cancer have reported associations between EZH2 overexpression and better prognosis." (PMID 26871294, 2016).
colorectal cancer (continued). "In a database comprising 301 patients with colorectal cancer, high EZH2 expression was inversely associated with miR-31 expression, independent of clinicopathological and molecular features." (PMID 26871294, 2016). "The present multivariate analysis showed that high EZH2 expression was inversely associated with miR-31 expression in colorectal cancer, whereas functional analysis showed that EZH2 knockdown increased miR-31 expression in colon cancer cell lines." (PMID 26871294, 2016). "In one of our previous studies, we undertook a case-control study to analyze associations between EZH2 polymorphisms (148505302C > T, 2110 + 6A > C and 626 − 394T > C) and colorectal cancer (CRC) risk." (PMID 25036033, 2014). "EZH2 over-expression is associated, in many aggressive tumours, with poor prognosis and presence of distant metastasis in colorectal cancer (CRC)." (PMID 25549357, 2014). "In our previous study, we observed that polymorphism in EZH2 gene 626 − 394T > C was observed to be associated with susceptibility of colorectal cancer." (PMID 25036033, 2014). "Indeed, loss of EZH2 expression at the tumor invasion front in colorectal cancer has been associated with a more aggressive phenotype and shorter survival due to reduced proliferation and acquisition of mesenchymal characteristics." (PMID 34140011, 2021). "Although our previous studies demonstrated the cancer-promoting role of EZH2 in the occurrence and progression of colorectal cancer in mice models, this study about glucose deprivation suggested that loss-of-EZH2 can also play a cancer promoting role in certain conditions." (PMID 34671029, 2021). "In conclusion, an inverse association was identified between EZH2 and miR-31 in colorectal cancers." (PMID 26871294, 2016). "In conclusion, we identified an inverse association between the expressions of EZH2 and miR-31 in colorectal cancer and that the upregulation of EZH2 expression may be a rare event in SSA/Ps." (PMID 26871294, 2016). "Moreover, in a study of colorectal carcinoma, it was reported that the C/C allelic variant of EZH2 was more significantly correlated with poor PFS and OS than were two other variants (C/T or T/T)." (PMID 25974088, 2015). "In order to obtain more information about epigenetic pathways with potential prognostic value in colorectal cancer, we performed multivariate survival analyses using combined expression data of multiple PcG proteins (EZH2, BMI1 and SUZ12) and their associated histone modification H3K27me3." (PMID 25243792, 2014). "The relationship between overall survival (OS) in colorectal cancer patients and the expression of miRs, which may target EZH2 and MFGE8 and have been linked to cancer, was examined using plasma and FFPE samples." (PMID 25081869, 2014). "EZH2 inhibition modulates the immune landscape in a mouse model of Lynch Syndrome colorectal cancer with promising insight for launching a phase 1 trial." (PMID 39946195, 2025). "Analysis of larger colorectal cancer datasets further revealed consistent upregulation of EZH2, EED, and UHRF1 in BRAF-mutant CRCs compared to BRAF-wildtype tumors, reinforcing the broader relevance of these findings." (PMID 40678543, 2025). "CD133 regulates the cell cycle in colorectal cancer stem-like cells by activating the WNT/β-catenin pathway via EZH2, which upregulates P21cip1 and promotes G1/S phase arrest." (PMID 39980929, 2025). "EZH2, a critical epigenetic regulator, is frequently overexpressed in various cancers, including breast, prostate, lung, hepatocellular, and colorectal cancers." (PMID 40038276, 2025). "We previously showed that AKT-mediated EZH2 phosphorylation induced EZH2 to interact with and methylate β-catenin in mesenchymal colorectal cancer (CRC) cells such as SW480." (PMID 39561122, 2024). "ZFAS1 facilitates the advancement and metastasis of colorectal cancer by serving as a competing endogenous RNA of miR-144 to modulate EZH2 expression." (PMID 39296014, 2024).
colorectal cancer (continued). "Inhibiting the activity of EZH2 can restore most of these transcriptomics and phenotypic effects in colorectal carcinoma cells." (PMID 38672463, 2024). "It was shown in the consequences that EZH2 exerted a positive feedback impact upon colorectal cancer progression." (PMID 38048186, 2023). "The correlation between EZH2 and apoptosis is supported by studies in which microRNA 26a targets Ezh2 to reduce EZH2 expression, inducing GCs apoptosis in mice or colorectal cancer cell apoptosis." (PMID 37963880, 2023). "It was shown in the CCK8 that EZH2 exerted a positive feedback effect upon colorectal cancer cell proliferation." (PMID 38048186, 2023). "The results illustrated that EZH2 was inversely proportional to the early apoptosis percentage of colorectal cancer cells." (PMID 38048186, 2023). "For example, lncRNA HOTAIR contributes to colorectal cancer and 5-FU resistance through the recruitment of EZH2 and subsequent silencing of miR-218, upregulation of VOPP1 expression and subsequent activation of the NF-κB/TS pathway." (PMID 37680988, 2023). "The cell scratch wound assay indicated that EZH2 has a positive feedback effect upon metastasis of colorectal carcinoma cells." (PMID 38048186, 2023). "LncRNA MSTO2P promoted colorectal cancer progression through epigenetically silencing CDKN1A mediated by EZH2." (PMID 35346226, 2022). "In summary, we found that MSTO2P was upregulated in CRC and promoted colorectal cancer progression through epigenetically silencing CDKN1A mediated by EZH2." (PMID 35346226, 2022). "Colorectal cancer (CRC) is a common malignant tumor that highly expresses EZH2, which has the third highest incidence and is the second leading cause of cancer-related death worldwide." (PMID 35432300, 2022). "Recent studies have indicated the significantly downregulated EZH2 expression in response to glucose deprivation in glucose-sensitive colorectal cancer cell lines in which the EZH2 knockout cells are more resistant to glucose deprivation." (PMID 36195655, 2022). "Several upstream molecules were shown to converge on EZH2 in colorectal cancer, potentiating its resistance to oxaliplatin." (PMID 36230683, 2022). "Mechanistically, SNHG6 down-regulates the expression levels of miRNA-214 and miRNA-26a/b via sponging to enhance EZH2 expression, leading to colorectal cancer progression." (PMID 35236381, 2022). "Investigation of molecular pathways reveals down-regulation of miRNA-154-5p by SNHG1 via sponging and EZH2 induction which increases colorectal cancer progression." (PMID 35236381, 2022). "A recent study showed that an EZH2 inhibitor increased the sensitivity to cytotoxic agent 5-fluorouracil through Smo/Gli-1 pathway in colorectal cancer." (PMID 33743723, 2021). "In particular, MALAT1 can activate EZH2 pathway in aggressive renal cell carcinoma, colorectal cancers and osteosarcoma 22-24." (PMID 34234858, 2021). "Silencing MALAT1 suppresses colorectal cancer cell proliferation as well as expression levels of EZH2 by upregulating miR-363-3p." (PMID 34660566, 2021). "Mechanistically, HDAC2 promotes epithelial‐mesenchymal transition (EMT) in colorectal cancer cells by combining HDAC1 with EZH2 (a key histone methyltransferase), possibly through the modular scaffold function of a new lncRNA, ENSG00000274093.1." (PMID 33325150, 2021). "Here through conditional screening of an epigenetic sgRNA library, we found that EZH2 played an important role in the tolerance of colorectal cancer cells to glucose deprivation." (PMID 34671029, 2021). "This supports previous findings identifying EZH2 as another chromatin regulator maintaining colorectal cancer stem cell (CCSC) functions." (PMID 33323965, 2021). "Recently, the lncRNA, SNHG6, was determined as a ceRNA to trap miR-26a and consequently promote EZH2 expression in colorectal cancer." (PMID 34512145, 2021).